IL19 (interleukin 19)
Diseases named in the same sentence as IL19 in open-access papers (continued):
Sharing a sentence is not in itself a finding about the gene and the disease.
tumor (continued). "Additionally, further studies using additional patient-derived samples are necessary to determine the IL-19 protein expression level and to assess whether IL-19 antibodies can effectively inhibit tumor progression." (PMID 40057744, 2025). "In addition, tumor cells expressed a much lower level of IL-19 than osteoclasts." (PMID 36006737, 2022). "To further elucidate the effects of IL-19 blockade in the tumor microenvironment, we examined the percentages of immune cell subpopulations in GBM-bearing mice after IL-19 antibody treatment." (PMID 40057744, 2025). "To investigate the effect of IL-19 blockade on modulating immune responses in TMZ-sensitive and TMZ-resistant GBM, we first compared the immune profiles between these tumor types." (PMID 40057744, 2025). "This core network of IL-19, TGFβ-1, CXCR4, BMP1, VCAN, and WNT2 reveals a tight-knit module that regulates tumor aggressiveness, immune evasion, and therapy resistance." (PMID 41348904, 2025). "However, the role of IL-19 in the GBM tumor microenvironment remains unknown." (PMID 40057744, 2025). "We obtained peritumoral tissue through MR-guided stereotaxic surgery and performed microarray analysis to investigate the Il-19 and its receptors expression levels in intratumoral and peritumoral region of human GBM tumor tissue." (PMID 40057744, 2025). "To assess IL-19 expression in human GBM in vivo, we intravenously administered CHOL-PEG-SPIO-IL19 nanoparticles to the tumor-bearing mice." (PMID 40057744, 2025). "PPI network analysis revealed these genes and modules were mainly related to tumor progression (LOXL1, IKBKE, LNX1, FOXA2, FGF17, and FGF2) and immune response (STAT4, IL23R, LTA, ITK, and IL19)." (PMID 36611170, 2023). "Taken together, blocking IL-19 could disturb the canonical IL-19/STAT3 pathway and weaken immunosuppressive tumor microenvironment in GBM." (PMID 40057744, 2025). "Next, we identified cell types with high expression of Il-19 in the GBM microenvironment, which included human and murine GBM cells (GBM8401, GBM8901, U87, and GL261) and two tumor-infiltrating subsets (microglia-like cells and MDSCs) in GL261 tumor-bearing mice." (PMID 40057744, 2025). "Thus, IL-19 is a promising theranostic target, acting as a double-edged sword to abrogate TAM-mediated immunosuppressive effects and tumor cell invasiveness." (PMID 40057744, 2025). "Additionally, IL-19 involved the role of MMP2, IL-6, MMP9, IL-1β, CXCR4, fibronectin, and TGF- β for tumor development." (PMID 37675062, 2023). "STAT3 knockdown abolished osteoclast- or IL-19–induced STAT3 phosphorylation in tumor cells, but did not affect upstream JAK1 phosphorylation." (PMID 36006737, 2022). "Immune cells that surround BE and EAC, including myeloid-derived suppressor cells, T-regulatory cells and Th17 cells, secrete proinflammatory cytokines including IL-6, IL-19, TNFα and TGF-β, resulting in a tumor permissive environment that promotes tumor cell survival, proliferation and metastasis." (PMID 35267943, 2022). "In contrast, IL-19, a cytokine of the IL-10 super-family, was detected at higher levels in the supernatant of Δ/Δ Pdgfrb tumor cells, perhaps compensating for the lack of IL-10." (PMID 36045346, 2022). "An important number of cytokine levels were below the detection limit of the method (LOD and/or LLOQ) such as IL-2, IL-10, IL-11, IL-12 (p40), IL-12 (p70), IL-19, IL-27 (p28), IL-28A/IFN-λ2, IL-29/IFN-λ1, IFN-α2 and osteocalcin in both tumor and normal tissue control samples." (PMID 33846436, 2021). "To validate IL-19 as an immunosuppressive cytokine that affects antitumor immunity, as indicated by the results of the human GBM tissue analysis, we applied IL-19 antibody treatment to block IL-19 function in GBM-bearing mice and examined survival outcomes and tumor growth." (PMID 40057744, 2025). "However, this blocking IL-19 did not affect Arg1 expression in M2-like macrophage subset (MC04) in TMZ-resistant GBM tumor (data not shown)." (PMID 40057744, 2025).
tumor (continued). "Finally, to assess whether host’s Il-19 affects GBM progression, we observed that the GL261 tumor burden was significantly lower in Il-19−/− mice compared to WT mice 21 days after tumor inoculation, indicating that host IL-19 promotes GBM progression." (PMID 40057744, 2025). "However, studies are yet to unravel the intracellular signaling triggered by IL-24 directing tumor cells to undergo cell death versus those mediated by IL-19 and IL-20 that do not trigger tumor cell death." (PMID 24377906, 2013). "It further supports that IL-19 not only directly facilitates cell proliferation, cell migration, and metastasis but it also prompts the expression of IL-1β, IL-6, TGF-β, MMP-2, MMP9, CXCR4, and fibronectin, which supply of a microenvironment for tumor growth and metastasis." (PMID 23710200, 2013).
infection (22 papers, 2014 to 2025). The state of being infected such as from the introduction of a foreign agent such as serum, vaccine, antigenic substance or organism. "We next identify a significant association of IL-19 and IL-24 secreting T cells with asymptomatic infection." (PMID 24699268, 2014). "Recent data from a mouse model of S. aureus, however, clearly reveals an important immuno-modulatory role for IL-19 and IL-24 in suppressing IL-1β and IL-17 dependent effector pathways and promoting susceptibility to infection." (PMID 24699268, 2014). "In plasma samples, IL-19 was detectable in healthy controls, and EV-A71 infection increased IL-19 levels in infected patients." (PMID 41550952, 2025). "In sera of WT mice, IL-20RA cytokines, but not IL-10, IL-12, or IFN-γ, were detected in mock-infected animals, and EV-A71 infection significantly increased IL-19 and slightly increased IL-20 levels." (PMID 41550952, 2025). "Our studies show that EV-A71 infection enhances IL-20RA cytokines, especially IL-19, in patients and in a murine model." (PMID 41550952, 2025). "EV-A71 infection enhanced IL-19 levels from 1 to 5 d.p.i., with significant increases on 3 and 5 d.p.i., and slightly increased IL-20 levels on 3 and 5 d.p.i. and IL-24 levels on 1 d.p.i.." (PMID 41550952, 2025). "In brains, IL-19 was detected in mock-infected mice, and EV-A71 infection increased IL-19 levels on 5 d.p.i.." (PMID 41550952, 2025). "Future studies are needed to find the signaling pathway regarding how EV-A71 infection increases IL-19." (PMID 41550952, 2025). "Flow cytometry analysis showed an increase in M-CSF, GM-CSF, IL-1 β, IL-8 and IL-19 for both post-infection samples compared to controls; in addition, ELISA assays indicated higher levels of M-CSF, GM-CSF and IL-1 α in the infected samples." (PMID 38774871, 2024). "In fact, their expression in lung tissues would suggest a role for IL-19 during the inflammatory response to infections." (PMID 36163397, 2022). "We observed that EV-A71 infection significantly increased serum and brain IL-19 levels in WT mice." (PMID 41550952, 2025). "Notably, both IL-19 and IL-20 suppress IL-12 in macrophages, which protects mice from EV-A71 infection." (PMID 41550952, 2025). "As all three mouse IL-20RA cytokines are constitutively expressed and IL-10 is induced after infection, this suggests that both IL-19 and IL-20 could be the upstream effectors to induce IL-10." (PMID 41550952, 2025). "Thirteen of the tested proteins (G-CSF, GM-CSF, M-CSF, TNF-β, IFN-gamma, TNF-α, IL-1 β, IL-3, IL-6, IL-7, IL-15, IL-17, IL-19) were found in the hemolymph and hemocytes of G. mellonella; however, the results regarding the influence of infection differed according to the detection method." (PMID 38774871, 2024). "In particular, some genes involved in immune/inflammatory responses and infection (e.g., IL19, MAPK15, and SERPINB10) and components of a complement system (e.g., C4B, VTN, BDKRB1, and C4BPA) have not been previously reported regarding their expression and functions in human omental adipose tissue." (PMID 30816281, 2019). "While the delayed production of IL-24 by activated astrocytes is similar to the production of IL-10 and IL-19 by these cells following infection and is consistent with a role in infection resolution, we have directly assessed the effect of this cytokine on inflammatory astrocyte responses." (PMID 30825881, 2019). "IL-19, IL-10, IL-6, IL-27 and IL-5 also increased during late infection days." (PMID 26070790, 2015). "Thus, the regulation of IL-10, IL-19 and IL-24 expression in filarial infection is dependent on the presence of active infection and therefore, curative treatment ablates the increase in the frequency of these predominantly regulatory T cells." (PMID 24699268, 2014). "Thus, the frequency of T cells expressing IL-10, IL-19, IL-24 and IL-26 are all decreased upon curative treatment, in contrast to that seen in those who continued to harbor infection." (PMID 24699268, 2014).
infection (continued). "This is further corroborated by the fact that filarial - antigen stimulation of PBMC cultures also resulted in significantly increased levels of total IL-19 and IL-24 in filarial infected individuals when compared to those with pathology and inactive infection." (PMID 24699268, 2014). "Indeed, anti-inflammatory genes exhibited a considerable presence in the infection setting; the IL-10 family of genes important for wound healing and repair (IL1r2, IL1r1, IL-24, IL-19, IL-22) were elevated >2- to 60-fold, although IL-10 itself remained unchanged." (PMID 40586608, 2025). "Furthermore, IL-19 is upregulated in macrophages after infection and reduces inflammation." (PMID 35638785, 2022). "Notably, IL-19 levels in these samples were significantly upregulated following the infection." (PMID 36163397, 2022). "As such, it is possible that this truncated protein serves as a decoy receptor for IL-19, and we have reported the intriguing finding that the expression of this receptor is downregulated following infection, an effect that could render CNS cells more susceptible to the effects of IL-19." (PMID 30542269, 2018). "Nevertheless, pretreatment with 1,25(OH)2D3 significantly suppressed IL-19 and CCL20 mRNA expression and decreased p-NF-κB protein levels induced by PEDV at 24 h post-infection in IPEC-J2 cells." (PMID 36142545, 2022). "These regulation of parasite antigen-specific IL-19 and IL-24 expressing CD8+ T cells are more dependent on the stage of the infection than on IL-10, IL-1β, and IL-23 as observed in the regulation of CD4+ T cell response." (PMID 34603287, 2021). "Finally, elimination of infection resulted in significantly decreased frequencies of antigen – specific CD4+ T cells expressing IL-10, IL-19 and IL-24." (PMID 24699268, 2014). "All infected IL-19-deficient mice (n = 10) and WT mice (n = 14) succumbed to death, suggesting that the effect of IL-20RA cytokines on EV-A71 infection may not be mediated by IL-19 alone." (PMID 41550952, 2025). "Treatment of filarial infection and consequent cure resulted in significantly decreased frequencies of CD4+ T cells expressing IL-10, IL-19, IL-24 and IL-26 after parasite-antigen stimulation whereas those who continued to harbor infection did not exhibit reduction in these frequencies." (PMID 24699268, 2014). "Interestingly, IL-20 has been previously shown to play a rather negative role in host defense; infection with Staphylococcus aureus led to the early up regulation of IL-20 family members (IL-19, IL-20 and IL-24), inhibiting the local generation of IL-1β and IL-17A." (PMID 26023727, 2015). "Unlike the IL-19 and CCL20 mRNA expression profiles, PEDV only increased IL-8 gene expression at an early time point post-infection." (PMID 36142545, 2022). "Results showed that pretreatment with 1,25(OH)2D3 significantly suppressed IL-8, IL-19, and CCL20 mRNA expression induced by PEDV at 1 h post-infection, but did not decrease p-NF-κB protein levels." (PMID 36142545, 2022). "Infection of DCs with Rift Valley Fever virus (RVFV) induces the expression of TNF-α, IL-6, and IL-10 but not IL-8, IL-19, or IL-1β17." (PMID 30401896, 2018). "Notably, SDAV uniquely induced cytokines like IL-1 alpha, IL-10, IL-19, IL-23, and IL-28, which were not significantly elevated in MHV-JHM infection." (PMID 40358160, 2025). "In the present study, mRNA coding for cytokines and cytokine receptors involved in the JAK-STAT pathway, including IL19, IL20, IL21R, and IL22RA2, were highly expressed in lower trachea during host-adapted swH1N1 infection compared to non-adapted huH1N1 infection." (PMID 39247193, 2024).
cancer (17 papers, 2013 to 2025). A tumor composed of atypical neoplastic, often pleomorphic cells that invade other tissues. "Interleukin-19 (IL19), a member of the IL-10 cytokine family, is an emerging immunomodulatory molecule implicated in inflammatory diseases and cancer." (PMID 40647365, 2025). "have reported that the gene encoding the cytokine IL-19, which is associated with inflammatory disorders and cancer, was induced in mouse and human cells in response to various cellular insults, including DNA damage." (PMID 36457703, 2022). "We also discovered that TOPK regulates another protein, IL19, which helps cancer cells grow and influences surrounding skin tissue." (PMID 40647365, 2025). "Secreted IL19, in turn, promotes cancer cell growth and acts in a paracrine manner on adjacent fibroblasts, enhancing their activation, as evidenced by the increased αSMA and FAPα expression." (PMID 40647365, 2025). "Maximum of the cancers displayed the pattern, with enhanced expression of IL19, TGFβ-1, CXCR4, BMP1, VCAN, and WNT2 protein levels in the samples of KICH, KIRC, LUAD, LUSC especially BRCA when compared to normal samples." (PMID 41348904, 2025). "After analyzing the expression profile of IL-19 in several cancers, we moved to develop a heat map of significant interleukins that depict a significant role in BC." (PMID 37675062, 2023). "IL-19 knockdown specimens showed inhibition in endogenous fibronectin expression and cancer cell migration." (PMID 37675062, 2023). "IL-19, IL-20, and IL-24 are expressed particularly by TH type 2 cells, which orchestrate protective type 2 immune responses and protective function in some cancers but also contribute to chronic inflammatory diseases." (PMID 40806452, 2025). "Such reciprocity between TOPK and IL19 creates a self-sustaining circuit that escalates malignancy." (PMID 40647365, 2025). "Previous studies have demonstrated that IL19 plays a critical role in cancer metastasis." (PMID 40647365, 2025). "In this regard, several studies demonstrate increased IL19 expression in cancer specimens." (PMID 40806452, 2025). "TIMER 2.0 analysis illustrates how numerous cancers have highly elevated IL-19 expression." (PMID 37675062, 2023). "Additionally, the GGI and PPI networks demonstrated that IL-19 had a substantial relationship with cytokine ligand interaction pathways, indicating a key role for IL-19 in cancer malignancy." (PMID 37675062, 2023). "In addition, GO enrichment analysis depicted that IL-19 was strongly engaged in cytokine receptor ligand activity leading to cancer tumorigenesis." (PMID 37675062, 2023). "Using the TIMER 2.0 database, it was determined how IL-19 was expressed in various cancers." (PMID 37675062, 2023). "The expression profile of IL-19 in several cancers including BC was evaluated here." (PMID 37675062, 2023). "In vitro studies have shown that the human EC cell line, CE81T expresses IL-19 as well as its receptor (Il-20R1/R2), and IL-19 can induce cancer cell proliferation, colony formation, and migration, which can be inhibited by anti-IL-19 antibody and anti-IL-20R1 antibody." (PMID 33390169, 2021). "IL-19 plays a critical role in tumorigenesis, triggering cell proliferation and mainly activating STAT3 in several cancer cells." (PMID 40806452, 2025). "By modulating key oncogenic pathways and promoting IL19 expression, TOPK contributes to a pro-tumorigenic microenvironment that supports both cancer cell proliferation and fibroblast activation." (PMID 40647365, 2025). "IL19 can directly influence immune cells, IL20 has a significant effect on skin inflammation, and IL24 can promote apoptosis of different types of cancer." (PMID 35883015, 2022). "Other cytokines like IL-6, IL-19, IL-20, TGF-α, TNF-α, and IL-23 are also known to promote cancer progression." (PMID 34681026, 2021). "IL-19 has emerged as a key player in TME modulation and cancer progression." (PMID 40806452, 2025).
kidney diseases (5 papers, 2013 to 2025). "Cytokines Il19 and Il24, implicated in epithelial injury and fibrosis in human kidney disease and in mouse models, were almost undetectable in control and strongly expressed in diseased kidney." (PMID 40533345, 2025). "We examined the renal presence of IL-19, IL-20, and IL-24, and their receptors in animal models of different kidney diseases and in renal biopsies of patients with different renal diseases." (PMID 32306980, 2020). "Our data confirmed the significance of IL-19, IL-20 and IL-24 in the pathomechanism of renal diseases." (PMID 32306980, 2020). "Recently, the role of IL-19, IL-20 and IL-24 has been reported in renal disorders." (PMID 32306980, 2020). "The expression of Il19, Il20 and Il24 increased in the animal models of various kidney diseases." (PMID 32306980, 2020). "However, the expression of IL-19 and its receptors on other cells in the kidney, namely renal fibroblasts and mesangial cells, may also contribute differently to kidney diseases." (PMID 23468852, 2013). "Renal Il19, Il20 and Il24 expression was determined in ischemia/reperfusion, lipopolysaccharide, streptozotocin, or UUO induced animal models of kidney diseases." (PMID 32306980, 2020).
inflammation (3 papers, 2019 to 2024). Aberrant reaction of the microcirculation characterized by movement of fluid and leukocytes from the blood into extravascular tissues. "In asthmatic mice, the degree of airway inflammation and IL-19 serum levels were lower in IL-20R1−/− mice and 51D-treated mice, which suggested that IL-19 levels are associated with the outcomes of airway inflammation." (PMID 31114590, 2019). "IL-24 and IL-19 are key factors in IBD-related intestinal inflammation and this is one of the few human studies to suggest that." (PMID 39007024, 2024).
neurodegenerative disease (2 papers, 2015 to 2021). A disorder of the central nervous system characterized by gradual and progressive loss of neural tissue and neurologic function. "Our results suggest that blockade of IL-19 signaling represents a potential therapeutic strategy for ameliorating neurodegenerative diseases including ALS." (PMID 33931083, 2021). "Further studies are needed to clarify whether additional administration of IL-19 could effectively slow and halt the progression of neurodegenerative diseases." (PMID 25794104, 2015). "Finally, to assess the involvement of IL-19 in neurodegenerative diseases, we investigated the expression pattern of IL-19 in a mouse model of AD using APP/PS1 Tg mice." (PMID 25794104, 2015). "However, it remains uncertain whether IL-19 is involved in the pathomechanism of neurodegenerative diseases." (PMID 33931083, 2021).
respiratory diseases (2 papers, 2022 to 2025). "IL-19 is supported by increasing evidences for a deleterious role in respiratory diseases." (PMID 35281428, 2022). "Accordingly, we speculated IL-19 expression in respiratory diseases might be deleterious." (PMID 35281428, 2022).
brain disorder (1 paper, 2018). A disease affecting the brain or part of the brain. "While it is clear that glia can be a significant source of IL-10, IL-19 and perhaps IL-20 and IL-24, and these resident CNS cells are responsive to their actions, the functions of the IL-10 cytokine family in health and brain disorders have been understudied." (PMID 30542269, 2018).